FGF21 (fibroblast growth factor 21)
Diseases named in the same sentence as FGF21 in open-access papers (continued):
Sharing a sentence is not in itself a finding about the gene and the disease.
Insulin resistance (continued). "Moreover, a recent study showed that circulating plasma levels of FGF-21 correlated directly with hepatic and whole-body (muscle) insulin resistance." (PMID 35883694, 2022). "In addition, plasma FGF21 levels are increased in subjects with prediabetes and type 2 diabetes, and correlate with hepatic and muscle insulin resistance in type 2 diabetes." (PMID 35163521, 2022). "•Deletion of GDF15 and FGF21 exacerbate insulin resistance in mice." (PMID 36064109, 2022). "Whether systemic FGF21 resistance exists or even promotes insulin resistance, is controversially discussed." (PMID 36034414, 2022). "For example, Irs1 phosphorylation at S302, S307, S522, and S636/639 have been linked to insulin resistance, but not all hormones that phosphorylate those Irs sites induce insulin resistance, including FGF21." (PMID 36169399, 2022). "Indeed, we have previously shown that adiponectin and FGF21 signaling pathways are completely abolished by resistin central treatment leading to hypothalamus inflammation and to overall insulin resistance." (PMID 36078135, 2022). "In conclusion, the results proved, for the first time, the potential positive effects of the phytochemicals from cocoa shell in preventing NAFLD by activating FGF21 signaling, oxidative stress, and mitochondrial dysfunction, and alleviating lipid accumulation and insulin resistance." (PMID 35052640, 2022). "3-OH-isobutyrate is a valine byproduct, and with FGF21 might be involved in protein-mediated insulin resistance in humans." (PMID 34553271, 2021). "Furthermore, studies in adults living with HIV infection show associations of high FGF21 or GDF15 levels with lipodystrophy, insulin resistance, cardiovascular disease, and overall mortality." (PMID 34972147, 2021). "Furthermore, in rats fed with high-fat diet, FGF-21 increases prior to the development of insulin resistance." (PMID 33924457, 2021). "Insulin resistance and FGF21 elevations were observed in overweight-obese PLWH." (PMID 34019585, 2021). "High baseline FGF21 levels are associated insulin resistance, which we did not observe in our cohort." (PMID 34858338, 2021). "It has also been shown that exogenous FGF21 treatment might increase microRNA (miRNA)-155-3p and miRNA-1968-5p to control hepatic energy metabolism in the state of insulin resistance." (PMID 34349728, 2021). "Recently, FGF21 has been proposed to link inflammation, insulin resistance and atherosclerosis." (PMID 33846498, 2021). "FGF21 ameliorates hepatic gluconeogenesis and insulin resistance." (PMID 33833309, 2021). "These may explain the inconsistency of the insulin resistance and FGF21 signal transduction between GDM-resistance women and T2DM patients." (PMID 34912302, 2021). "Interestingly, we also found that GDF15 protects against hepatic steatosis and insulin resistance in mice fed an HFD, which was in contrast to our finding of fewer hepatic lipid droplets in FGF21-deficient mice." (PMID 33718833, 2021). "Additionally, they noted that serum FGF21 levels positively correlated with insulin resistance and serum triglyceride levels." (PMID 34769010, 2021). "Similarly, there was a correlation between FGF21 and parameters of glycaemic dysregulation–blood glucose, as well as with insulin resistance as measured by HOMA‐IR (p < 0.03, for both comparisons)." (PMID 34141520, 2021). "Consequently, the HOMA-IR value, a surrogate marker of insulin resistance, was lower in the FGF21-treated group than in the control group, which was consistent after being adjusted for final body weight." (PMID 32957703, 2020). "Beyond the renal clearance, accumulation of FGF21 may contribute by insulin resistance, chronic inflammation, and increased oxidative stress in uremic circumstances." (PMID 32188054, 2020). "Current findings imply that propofol may turn into insulin-sensitizing molecules during situations of existing insulin resistance, which involve FGF-21, GLP-1, and ER stress." (PMID 32679813, 2020).
Insulin resistance (continued). "In the present study, we hypothesized that increases in hepatic FGF21 expression and circulating FGF21 levels precede diet-induced insulin resistance and hyperglycemia, which may be related to the increased expression of hepatic htr2a and Sdf2l1." (PMID 32978487, 2020). "Additionally, administration of a known FAP inhibitor (Talabostat, TB) to diet-induced obese mice improved insulin resistance and increased endogenous intact FGF21 level." (PMID 33277568, 2020). "In addition, subcutaneously injection of recombinant human FGF-21 improved cognitive function via attenuating insulin resistance and inflammatory response in an obese mouse model." (PMID 31900170, 2020). "Further, adipo-specific DNMT3A-KO mice were protected from diet-induced insulin resistance and glucose intolerance, adipocyte Fgf21 was identified as a target gene inhibited by DNMT3A, and intriguingly, DNA methylation at the Fgf21 gene was elevated in adipose tissue of diabetic patients." (PMID 33235221, 2020). "FGF21 is an endocrine hormone that plays an important role in energy homeostasis, insulin resistance, dyslipidemia, as well as fatty liver disease, and elevation of FGF21 action is an attractive, new therapeutic strategy for the treatment of metabolic diseases including diabetes." (PMID 33277568, 2020). "Not only depleted circulating FGF21, but also higher circulating FGF21 in mice fed a high-fat diet might contribute to insulin resistance." (PMID 32978487, 2020). "Furthermore, FGF21 acts as an insulin sensitizer in mice to overcome peripheral insulin resistance induced by fasting in mice, an effect that is decreased in BAT of liver-specific FGF21 KO mice." (PMID 31918921, 2020). "In this study, we demonstrated that weight gain, glucose intolerance and insulin resistance in HFD-fed mice could be reversed by an application of the FGF21 mimetic CVX343." (PMID 31121855, 2019). "The AhR protects against fatty liver induced by insulin resistance by activating FGF21." (PMID 31638212, 2019). "However, in humans, circulating FGF21 levels are often elevated in different pathophysiological conditions such as metabolic syndrome, obesity, dyslipidemia, insulin resistance, type 2 diabetes, non-alcoholic fatty liver disease and coronary artery disease." (PMID 31712677, 2019). "The glucose‐lowering effects of thiazolidinediones are due to increased disposal of glucose into adipose tissues along with increased expression of insulin sensitizing factors, such as adiponectin, and decreased expression of proteins that promote insulin resistance such as FGF‐21." (PMID 31782258, 2019). "We further explored the effect of FGF21 on insulin resistance." (PMID 29311680, 2018). "Thus, FGF21 protects muscle tissue against insulin resistance, augments brown fat thermogenesis in concert with irisin, and is related to weight loss and WAT browning." (PMID 30559681, 2018). "FGF21 phosphorylates Akt and ameliorates insulin resistance in peripheral tissues." (PMID 30355361, 2018). "TZDs inhibit the expression of TNF-α, IL-6, and resistin in adipose tissue, which promote insulin resistance and chronic inflammation, while TZDs increased the production of adiponectin and fibroblast growth factor 21 (FGF21), which enhance fatty acid oxidation and insulin sensitivity." (PMID 30079233, 2018). "Furthermore, FGF-21 has also shown to prevent palmitate-induced insulin resistance in primary human myotubes by inhibiting stress kinases and NF-κB." (PMID 29760587, 2018). "Interestingly, FGF21 gene transfer has been shown to significantly reduce hyperinsulinemia and attenuate insulin resistance in mice fed a HFD, leading to significant improvements in glucose tolerance." (PMID 30355361, 2018). "Serum FGF21 levels were significantly increased in patients with insulin resistance and T2DM." (PMID 30185439, 2018).
Insulin resistance (continued). "The increase in circulating FGF21 levels might also reflect a protective compensatory response to insulin resistance, hyperlipidemia, and the increase in systemic inflammation in patients with atherosclerotic diseases." (PMID 30185439, 2018). "Our study raises the possibility that targeting subcutaneous fat expansion through manipulation of FGF21 may represent a therapeutic strategy to combat insulin resistance and type 2 diabetes." (PMID 29348470, 2018). "Furthermore, PGE1 promoted the protein expression of autophagy-related fibroblast growth factor-21 (FGF21), which alleviated insulin resistance." (PMID 29311680, 2018). "However, Klb AdipoKO mice are refractory to the effects of physiological concentrations of FGF21 on the alleviation of glucose intolerance and insulin resistance." (PMID 29348470, 2018). "Combined with the results in vitro, PGE1 may ameliorate insulin resistance in proximal tubule through the suppression of autophagy and the upregulation of its downstream molecualar FGF21, consequently resulting in relieving the kidney dysfunction." (PMID 29311680, 2018). "Here, we show that a majority of patients with KLB mutations (9/13) exhibit hypogonadotropic hypogonadism with some degree of metabolic defect (i.e. overweight, insulin resistance, and/or dyslipidemia), consistent with the metabolic role of FGF21/KLB/FGFR1 pathway." (PMID 28754744, 2017). "Since the FGF21’s improvement of insulin resistance is largely attributed to enhanced insulin action in the liver, we suggest that the EPO’s enhancement of BAT derived-FGF21 secretion contributes to the reduction of gluconeogenesis of liver in induced obese mice on a high-fat diet." (PMID 28288167, 2017). "FGF-21 might be an important endocrine agent in PD patients and could act as hormonal signaling to maintain glucose homeostasis and prevent potential insulin resistance." (PMID 26986485, 2016). "FGF-21 is also involved in the regulation of body fat and is directly correlated with body mass index (BMI), leptin, triglycerides, insulin and the homeostatic model assessment of insulin resistance (HOMA-IR) index." (PMID 26986485, 2016). "Many studies have demonstrated that FGF21 had insulin-like effects, which could function as an effective metabolic regulator of glucose and lipid homeostasis in the context of insulin resistance, glucose intolerance, and dyslipidemia." (PMID 27190511, 2016). "Our results indicated, for the first time, that APL maybe served as a PPARγ agonists and improved insulin resistance partially via activation of PPARγ and subsequent regulation of FGF21- AMPK signaling pathway." (PMID 27391974, 2016). "However, plasma C18:0 was the only ceramide correlating positively with circulating FGF‐21 and inversely with adiponectin, further supporting a potential deleterious role for this ceramide in insulin resistance." (PMID 26916476, 2016). "In addition, the higher level of FGF21 is compensatory for the insulin resistance and is response to downregulation of blood glucose." (PMID 27190511, 2016). "These preliminary results suggest that FGF-21 might play a protective role as against the development of insulin resistance over time in patients undergoing a continuous glucose load." (PMID 26986485, 2016). "This high production of FGF-21 might explain the tendency toward insulin resistance that PD patients could exhibit due to glucose absorption from their dialysate (estimated between 100–300 g per day)." (PMID 26986485, 2016). "In conclusion, these preliminary results suggest that FGF-21 might be protective against the development of insulin resistance over time in patients undergoing a continuous glucose load." (PMID 26986485, 2016). "Here, for the first time, we provide evidence that APL could improve insulin resistance, partially through activating PPARγ and subsequently regulating FGF21-AMPK signaling pathway." (PMID 27391974, 2016).
Insulin resistance (continued). "In this study, we found that loss of FGF21 in vivo led to increased insulin resistance without changes in glycemia." (PMID 25811804, 2015). "This suggests that FGF21 might have a role in the regulation of metabolism, and provide some explanation of the link between insulin resistance and PE." (PMID 25890271, 2015). "FGF21-KO mice were less insulin sensitive than WT mice with higher blood glucose concentrations at 15 min and 30 min after insulin injection and consistently, the ‘homeostasis model assessment' (HOMA-IR) index, which measures the degrees of insulin resistance, was also increased in FGF21-KO mice." (PMID 25811804, 2015). "Because FGF21 and insulin action are likely interacting, we proposed that, similarly to insulin resistance, ectopic lipid accumulation could impair FGF21 signaling." (PMID 25973847, 2015). "FGF21 is independent of adiposity in children, and the significant metabolic effect seems to be limited to pathological conditions associated with insulin resistance." (PMID 24883065, 2014). "In children, knowledge on FGF21 and insulin resistance is limited." (PMID 24883065, 2014). "We found that muscle FGF-21 mRNA was negatively associated with the insulin-mediated glucose-uptake, but not with hepatic insulin resistance (data not shown)." (PMID 23533568, 2013). "Moreover, the enhanced serum FGF21 level has been correlated to presence of insulin resistance, and increased levels of TC and TG." (PMID 23981342, 2013). "Additionally, serum FGF21 levels independently and positively correlated with insulin resistance and serum triglycerides." (PMID 24260557, 2013). "Paradoxical upregulation of FGF21 might be a compensatory mechanism to improve glucose metabolism when insulin resistance and an adverse lipid profile are present." (PMID 24260557, 2013). "FGF21 has potential insulin mimetic effects on lowering plasma glucose and liver lipid levels, suggesting that FGF21 may play a role in the pathogenesis of liver and whole-body insulin resistance in T2DM17." (PMID 24189525, 2013). "In summary, the central actions of FGF21 in GDM subjects may be pivotal in the pathogenesis of insulin resistance in GDM subjects." (PMID 23755203, 2013). "Therefore, increased levels of circulating FGF-21 have been suggested to be a compensatory mechanism due to insulin resistance or a sign of FGF-21 resistance." (PMID 23533568, 2013). "The central actions of FGF21 in GDM subjects maybe pivotal in the pathogenesis of insulin resistance in GDM subjects." (PMID 23755203, 2013). "Alternatively, the altered expression of FGF19 and/or FGF21 may be involved in a complex adaptive response to these diseases, or a phenomenon reminiscent of hyperinsulinemia and insulin resistance." (PMID 24260557, 2013). "Another plausible explanation for the protection against insulin resistance by MR on mice fed HFD could be on the effects of FGF21." (PMID 23236485, 2012). "Liraglutide treatment markedly improved insulin resistance and increased FGF-21 expression in liver and FGFR-3 in adipose tissue, restored β-Klotho mRNA expression in adipose tissue as well as FGFR-1-3, β-Klotho levels and phosphorylation of FGFR1 up to the levels observed in control mice in liver." (PMID 23152772, 2012). "Decreased circulating FGF-21 after CSII treatment might also mediate the improvement of insulin resistance in the nT2DM patients." (PMID 22046277, 2011). "Interestingly, along with the rapid improvement in glucose-lipid metabolism and insulin resistance, and elevated plasma insulin, we observed a dramatic decrease in fasting plasma FGF-21 concentrations in these patients." (PMID 22046277, 2011). "The upregulation of serum FGF21 levels might be a compensatory mechanism to improve glucose metabolism when insulin resistance is present." (PMID 21331285, 2011).
Insulin resistance (continued). "This study investigates whether methionine restriction can mitigate high-fat diet-induced alterations in insulin resistance and neuroinflammation in male and female mice and explores the role of endogenous fibroblast growth factor 21 (FGF21) in mediating these effects." (PMID 41805916, 2026). "Additionally, this study highlighted a correlation between FGF-21 levels and insulin resistance indicators, such as fasting insulin, measurements from the first and second hours of the oral glucose tolerance test (OGTT), and the HOMA index, as well as triglycerides, HDL, VLDL, uric acid, and GGT." (PMID 40559404, 2025). "In adipose tissues of obese mice, impaired FGF21 signaling cascades led to a defect in the ability of FGF21 to induce GLUT1-dependent glucose uptake and ADP secretion, thereby resulting in insulin resistance, while FGF21 infusion could improve glucose uptake and insulin sensitivity in obese mice." (PMID 40756666, 2025). "Moreover, data on insulin resistance and lipid profiles, which have been shown in previous studies to be associated with circulating FGF21 levels, were not available in our dataset." (PMID 40563517, 2025). "Therefore, the elevated FGF21 concentrations observed in the IGT&T2D group may reflect a compensatory mechanism to improve insulin resistance by stimulating glucose uptake." (PMID 40377893, 2025). "Therefore, FGF21 dampened glucose flux in conditions of insulin resistance." (PMID 39962359, 2025). "FGF21 might play a role in reducing GH-induced insulin resistance after bariatric surgery." (PMID 39100807, 2024). "In addition, FGF21 has been shown to suppress adipose tissue lipolysis, increase adiponectin levels and decrease insulin resistance which also may impact hepatic steatosis." (PMID 37355760, 2023). "Treatment with recombinant FGF21 in diet-induced obese mice and other animal models reduced TG levels and ameliorated hepatic steatosis via inhibiting the lipogenic gene expression (srebp-1), stimulating brown adipose tissue and browning white adipose tissue, and improving insulin resistance." (PMID 37641103, 2023). "FGF21 may improve insulin resistance through different pathways." (PMID 37576954, 2023). "Importantly, this suggest that, despite the fact that FGF21 is beneficial for insulin resistance and type 2 diabetes, long-term use of FGF21 may lead to increased bone fragility." (PMID 36967758, 2023). "Additionally, betaine supplementation may increase circulating and hepatic fibroblast growth factor 21 levels, thereby increasing whole-body energy expenditure, maintaining glucose homeostasis and improving insulin resistance." (PMID 35057543, 2022). "Additionally, FGF21 levels were directly correlated with peripheral and hepatic insulin resistance." (PMID 36415151, 2022). "Importantly, melatonin did protect against inflammation or insulin resistance in FGF21−/− mice." (PMID 36207302, 2022). "In addition, FGF-21 could be used as a good biomarker for diseases such as non-alcoholic fatty liver disease, insulin resistance, dilated cardiomyopathy, and old age related cachexia." (PMID 33810243, 2021). "This is exciting as adipocytes are a well-known target of FGF21 and intramuscular adipose tissue (IMAT) has emerged as an important player in insulin-resistant associated diseases; high levels of IMAT are associated with insulin resistance and loss of muscle strength." (PMID 33762965, 2021). "FGF21 resistance impairs its ability to stimulate adiponectin secretion in adipose tissue, and chronic inflammation may mediate the relationship between the dysfunctional FGF21-adiponectin pathway and insulin resistance." (PMID 34321008, 2021). "Moreover, recent studies had shown that FGF-21 could be a potential predictor for fatty liver, dilated cardiomyopathy, insulin resistance, and cachexia." (PMID 33810243, 2021).